AQP2 (aquaporin 2)
Diseases named in the same sentence as AQP2 in open-access papers (continued):
Sharing a sentence is not in itself a finding about the gene and the disease.
kidney cancer (1 paper, 2022). Primary or metastatic malignant neoplasm involving the kidney. "This study not only provides a reference for the discovery of new targets for kidney cancer treatment, but also broadens the current new understanding of the function of the AQP2 protein." (PMID 36117171, 2022). "This study found and confirmed for the first time that MIAC directly binds to AQP2 inhibiting the expression of EREG, EGFR and the activation of downstream PI3K/AKT and mTOR signaling pathways to achieve the inhibitory effect of kidney cancer growth and metastasis." (PMID 36117171, 2022).
Liddle syndrome (1 paper, 2023). A rare genetic form of low-renin hypertension characterized by hypertension associated with decreased plasma levels of potassium and aldosterone. "For example, tubuloids can be obtained from existing mouse (knockout or mutation) models of the V2R, AQP2, and ENaC, thereby providing a model for e.g. hereditary NDI and Liddle’s syndrome." (PMID 36760360, 2023).
lung carcinoma (1 paper, 2014). "The main polymorphisms on transporters OCT2, LRP, AQP2, AQP9 and TMEM205 genes were genotyped in 338 lung cancer patients." (PMID 24643204, 2014). "In conclusion, the genetic polymorphisms in OCT2, AQP2, AQP9 and TMEM205 may contribute to chemotherapy response in lung cancer patients." (PMID 24643204, 2014). "Our results showed that SNPs rs195854 (OCT2) and rs186941 (OCT2), rs7314734 (AQP2), rs1516400 (AQP9), and rs896412 (TMEM205) might be related with chemotherapy response in lung cancer patients." (PMID 24643204, 2014).
lupus (1 paper, 2025). "The authors reported an increase in AQP1 expression in lupus glomeruli and a decrease in AQP1, AQP2, and AQP3 expression in renal tubules based on immunohistochemistry (IHC)." (PMID 40072108, 2025).
lupus nephritis (1 paper, 2025). Glomerulonephritis in the context of systemic lupus erythematosus. "A 2003 study performed using several types of glomerulonephritis including 4 lupus nephritis suggested a decrease in the expression of AQP2 and AQP3 and an increase in the expression of AQP1 in pathological glomeruli." (PMID 40072108, 2025). "Further research is warranted to evaluate AQP1, AQP2, and AQP3 as prognostic markers in both urinary and histological assessments of lupus nephritis." (PMID 40072108, 2025). "In lupus nephritis (LN), although we observed a reduction in staining for AQP1, AQP2, and AQP3; their localization remained unchanged." (PMID 40072108, 2025). "The aim of this study is to characterize the tubular expression of AQP1, AQP2 and AQP3, which could provide a better understanding of tubulointerstitial stress during lupus nephritis." (PMID 40072108, 2025).
malaria (1 paper, 2023). Malaria is a serious and sometimes fatal disease caused by a parasite that commonly infects a certain type of mosquito which feeds on humans. "Phylogenetic analysis confirms that AQP2 is unique to malaria and closely related parasites and most closely resembles intracellular aquaporins." (PMID 37883438, 2023). "Generation and phenotypic characterization of knockout parasites confirmed that AQP2 is important for production of sporozoites in both the rodent and human parasites and for malaria transmission in rodents." (PMID 37883438, 2023). "This in conjunction with the importance of AQP2 for malaria transmission suggests that AQP2 may be a fruitful target of antimalarial interventions." (PMID 37883438, 2023).
minimal change disease (1 paper, 2013). "Accordingly, we investigated AQP5 and AQP2 expression by IF in kidney biopsies from 17 patients with DN and 15 with minimal change disease (MCD)." (PMID 23326416, 2013).
neurohypophyseal diabetes insipidus (1 paper, 2012). Hereditary central diabetes insipidus is a rare genetic subtype of central diabetes insipidus (CDI) characterized by polyuria and polydipsia due to a deficiency in vasopressin (AVP) synthesis. "In mice, mutations in the vasopressin-neurophysin II gene have been associated with familial neurohypophyseal diabetes insipidus, and the S256L mutation in aquaporin-2 has been associated with congenital progressive hydronephrosis." (PMID 23130747, 2012).
Palmoplantar keratoderma (1 paper, 2023). Abnormal thickening of the skin of the palms of the hands and the soles of the feet. "These diseases include cataract (AQP0), autosomal recessive nephrogenic diabetes insipidus (AQP1 and AQP2) and palmoplantar keratoderma (AQP5) and diminished glycerol release (AQP7)." (PMID 36913438, 2023).
periodontitis (1 paper, 2020). An acute or chronic inflammatory process that affects the tissues that surround and support the teeth. "We show that variation in AQP2 are potentially associated with temporomandibular joint disorder and periodontitis." (PMID 32130259, 2020). "However, when TMD and periodontitis were combined, a marker in AQP2 (rs3741559) showed and association (p = 0.02)." (PMID 32130259, 2020). "Combined analysis of TMD and periodontitis showed an association with rs3741559 in AQP2 (p = 0.02)." (PMID 32130259, 2020). "Associations were found between the single nucleotide polymorphism (SNP) rs467323 in AQP2 and TMD in both genotypic (p = 0.03) and recessive (p = 0.02) models, and between rs1996315 in AQP6 and periodontitis (p = 0.05)." (PMID 32130259, 2020).
polyp (1 paper, 2023). A usually exophytic mass attached to the underlying tissue by a broad base or a thin stalk. "In polyp samples from patients treated with fluticasone propionate in the 7 days before sinus surgery, there was a decrease in the expression of aquaporin-2 and aquaporin-5 compared to the control group." (PMID 37109177, 2023).
renal hypertension (1 paper, 2022). Hypertension caused by the kidney's hormonal response to narrowing or occlusion of the renal arteries. "In renal hypertension, decreased AVP sensitivity and increased NF-κB activity in renal marrow collecting tubes may lead to decreased AQP2 expression." (PMID 35721542, 2022).
renovascular hypertension (1 paper, 2022). High blood pressure secondary to renal artery stenosis. "Also, the suppressed expression of the AQP2 mRNA in the kidney from renovascular hypertension supports the previous report." (PMID 35722149, 2022).
selenium deficiency (1 paper, 2021). A nutritional deficiency disease resulting from inadequate selenium levels in the body, which can lead to impaired function of selenoproteins essential for antioxidant defense and thyroid hormone metabolism. "However, neither Aqp2 nor Avpr2 mRNA were affected by maternal selenium deficiency." (PMID 33769708, 2021).
trypanosomiasis (1 paper, 2017). Infection with protozoa of the genus trypanosoma. "Melarsoprol has been highly effective against trypanosomiasis but clinical resistance, due to an aqp2-defect, has become widespread." (PMID 28358927, 2017).
type 2 diabetes (1 paper, 2024). "This is consistent with the results of the present study, because not only the expression of AQP2, but also the expression of V2R were decreased in animals with induced type 2 diabetes compared with control animals, which may indicate that a high-fat diet may affect the V2R-AQP2 regulatory pathway." (PMID 38791455, 2024). "Results unveiled notable alterations in water intake, body and kidney mass, kidney morphology, fatty acids, AQP2, AVPR2, AcetylCoA, SREBP-1, blood urea, creatinine, and glucose levels in control rats with induced type 2 diabetes." (PMID 38791455, 2024).
Wilms tumor (1 paper, 2021). An embryonal neoplasm characterized by the presence of epithelial, mesenchymal, and blastema components. "Therefore, the development of vaccines for AQP2 can further serve the clinical application of Wilms tumor treatments." (PMID 34422051, 2021).
ZIKV infection (1 paper, 2019). "We found that both of ZIKV infection and recombinant IL-1β treatment resulted in a significant decrease expression of AQP1 and AQP2 in primary murine renal epithelial cells thus inducing water re-absorption disorder, which indicated that inflammasome was involved in ZIKV-induced renal dysfunction." (PMID 31474993, 2019).
kidney disease (14 papers, 2017 to 2025). "When the YAP gene is deficient, the mRNA and protein abundance of Aqp2 in the kidneys is significantly reduced, leading to disorders in renal water—salt metabolism and further promoting the progression of kidney diseases." (PMID 40078458, 2025). "Congenital nephrogenic diabetes insipidus (CNDI) is a rare renal disorder caused by mutations in arginine vasopressin receptor 2 (AVPR2) or aquaporin 2 (AQP2)." (PMID 32083042, 2020). "Notably, exosomal proteins such as aquaporin-1 (AQP1) and aquaporin-2 (AQP2) have been discovered as possible kidney disease biomarkers." (PMID 39728069, 2024). "Similar to AQP4, AQP2 not only influences fluid transport in many epithelial and endothelial tissues, but also participates in the regulation of inflammation and apoptosis in renal diseases." (PMID 35386692, 2022). "In addition to AQPs, AQP2 participates in the regulation of inflammation and apoptosis in renal diseases." (PMID 35386692, 2022). "Moreover, the relationship between AQP2 and AVPR2 and the localization of these proteins’ expression in dogs with renal disease have rarely been investigated." (PMID 34903939, 2021). "However, the release of uEV‐AQP1 and ‐AQP2 has not yet been investigated in human kidney diseases." (PMID 34435473, 2021).
tumor (14 papers, 2013 to 2025). "Based on the regulation of the biological metabolism of water, AQP2 was reasonably assumed to participate in the tumor microenvironment." (PMID 36254092, 2022). "Interact with AQP2 to inhibit tumor growth and metastasis of HNSCC by regulating the actin cytoskeleton of SEPT2 and ITGB4." (PMID 34888249, 2021). "Materials and Methods: IHC and PT-PCR were used to detect ENaCα, β, γ, AVPR2, AQP2, and MR expression in the primary tumor and peritumoral tissues." (PMID 33193899, 2020). "In this paper, we find AQP2 is decreased in tumor tissue; however, AQP2 cannot affect the staging and prognosis in RCC." (PMID 33193899, 2020). "We have shown that hyperosmolality regulates the expression of several hundred genes (including Aqp2), that this expression pattern inversely correlates with ccRCC tumor samples, and that this can be used for prediction of cancer-specific survival." (PMID 32059438, 2020). "Further mechanistic studies have demonstrated that MIAC directly bind to AQP2 protein, inhibit EREG/EGFR expression and activate downstream pathways PI3K/AKT and MAPK to achieve anti-tumor effects." (PMID 36117171, 2022). "Beyond that, 2 genes (AQP2, KCNJ1) were selected to analyze their relationship with tumor expression and clinical stage." (PMID 36313709, 2022). "We found that AQP1 (5.83e−07), AQP2 (0.0146), AQP4 (0.000382), AQP6 (0.0221), AQP7 (0.00052), AQP9 (8.2e−07) had significant correlations with the pathological stages of the tumor." (PMID 35245343, 2022). "At the same time, although the mRNA expression level of AQP2 was related to tumor grade, it had no significant statistical significance with the patient’s OS and DFS." (PMID 35245343, 2022). "First, we categorized clustered data into tumor and stromal populations using a panel of markers for each (epithelial: AQP1, AQP2, EPCAM; endothelial: PLVAP, CD31, CD34; fibroblast: PDGFRα, PDGFRβ; immune: CD45; tumor cell: CXCR4, VIM, KRT18, PAX8, PAX2, CA9, CD10)." (PMID 34884982, 2021). "Not to our surprise, bioinformation analysis display that AQP2 is failed to regulate immune cell constitution in the tumor microenvironment." (PMID 33193899, 2020).
cancer (8 papers, 2018 to 2025). A tumor composed of atypical neoplastic, often pleomorphic cells that invade other tissues. "The expression of ENaCα, β, γ, AQP2, AVPR2, and MR decreased in cancer tissue." (PMID 33193899, 2020). "But so far, the role of AQP2 in cancers has not yet been explored." (PMID 29472315, 2018).
infection (3 papers, 2014 to 2019). The state of being infected such as from the introduction of a foreign agent such as serum, vaccine, antigenic substance or organism. "Previous studies have shown that infection with the murine A/E pathogen C. rodentium resulted in mislocalization of the water channels aquaporin 2 and 3 (AQP2 and AQP3) from the host cell membranes to the cytoplasm." (PMID 31242273, 2019).
kidney (2 papers, 2021 to 2022). "Apical trafficking of AQP2 in the principal cell also diminishes in I/R-induced kidney injury." (PMID 35327416, 2022). "So far, we have shown that the release of AQP1‐ and AQP2‐bearing uEVs (uEV‐AQP1 and ‐AQP2) are altered in experimental kidney injury models such as gentamicin, cisplatin, puromycin aminonucleoside, and ischemia/reperfusion (I/R) models." (PMID 34435473, 2021).
bacterial infection (1 paper, 2019). "In contrast, bacterial infection has been shown to interfere with Aqp2 mRNA and AQP2 protein expression, via activation of the inflammatory pathway, involving NF-κB in vivo, and using LPS in cultured renal CCD mpkCCDcl4." (PMID 31671521, 2019).
Cardiovascular Diseases (1 paper, 2016). "This review focuses on mechanisms controlling the localization of AQP2 and the value of such control mechanisms as pharmacological targets in cardiovascular diseases." (PMID 26903868, 2016).
genetic disorder (1 paper, 2021). "Congenital nephrogenic diabetes insipidus (CNDI) is a genetic disorder caused by mutations in arginine vasopressin receptor 2 (AVPR2) or aquaporin 2 genes, rendering collecting duct cells insensitive to the peptide hormone arginine vasopressin stimulation for water reabsorption." (PMID 33804115, 2021).
AQP2 also shares sentences with these, for which no sentence is quoted: liver cirrhosis (8 papers); nephrogenic syndrome of inappropriate antidiuresis (4); Bartter syndrome (3); Hyperglycemia (3); autosomal nephrogenic diabetes insipidus (2); cystic fibrosis (2); essential hypertension (2); hereditary clear cell renal cell carcinoma (2); IgA nephropathy (2); Obesity (2); polycystic kidney (2); syndrome of inappropriate antidiuretic hormone secretion (2); 21-hydroxylase deficiency (1); adrenal cortical tumors (1); anemia (1); brain cancer (1); Cerebral Edema (1); cholestasis (1); chromophobe renal cell carcinoma (1); clear cell renal cell carcinoma (1); colorectal cancer (1); congenital adrenal hyperplasia (1); COVID-19 (1); Diarrhea (1); distal renal tubular acidosis (1); electrolyte disorders (1); electrolyte imbalance (1); end-stage renal disease (1); endocrine disorder (1); endometrioid ovarian cancer (1).
A further 34 diseases each share a sentence with AQP2 in 1 paper.